MMP9 (matrix metallopeptidase 9)
Diseases named in the same sentence as MMP9 in open-access papers (continued):
Sharing a sentence is not in itself a finding about the gene and the disease.
lung carcinoma (continued). "Our data supported the notion that the over-expression of miR-329 was associated with the down-regulation of MMP-7 and MMP-9 levels in lung cancer cells (A549 and H1299), which further confirmed the inhibitory role of miR-329 on invasion and migration of NSCLC cells." (PMID 26909600, 2016). "When we carried out the stratified analysis by selected variables, an association was found between the polymorphism in the MMP9 gene and the lung cancer risk for age and smoking status (adjusted OR = 0.07; 95% CI: 0.01-0.58; and adjusted OR = 0.28; 95% CI: 0.08-1.01, respectively) [Data not shown]." (PMID 22455335, 2012). "Indeed, the enhanced expression of MMP-9 has been associated with human lung cancer invasion and metastasis." (PMID 19568240, 2009). "Furthermore, there is a positive association between MMP9 expression and lung cancer severity." (PMID 39991567, 2025). "Next we investigated whether the MMP-2-735C/T and MMP-9-1562C/T genotypes were associated with environmental factors in lung cancer patients and healthy controls, as well as clinicopathological characteristics in lung cancer patients." (PMID 37445754, 2023). "Some studies have found that the C allele of genetic polymorphism in MMP-9 gene rs3918242 was significantly associated with an increased risk for the lung cancer patients, but the details on how genetic variant impacts MMP13 expression is still largely unknown." (PMID 30889876, 2019). "A previous study reported that cisplatin and berberine inhibit the MMP-2 and MMP-9 pathways, reducing cell proliferation and inducing apoptosis in lung cancer." (PMID 40217305, 2025). "In this research, we measured circDENND4C, miR-200b, and MMP-9 abundance in NSCLC cell lines, and analyzed the function of circDENND4C, miR-200b, and MMP-9 contributing to lung cancer progression in vitro." (PMID 40034591, 2025). "Blocking PARP-1 significantly reduces the levels of ALOX5 and MMP-9 and inhibits neutrophil-mediated lung cancer cell invasion and tumor growth in vivo." (PMID 41155938, 2025). "In A549 lung cancer cells, Xn (10 μM) significantly suppressed MMP-9 expression, as confirmed by Western blot analysis." (PMID 40563423, 2025). "ADAR1 and MMP-9 levels showed a strongly positive correlation (P=6.45×10-34) in 10 lung cancer cell lines, highest in H1581." (PMID 41309247, 2025). "In conclusion, our findings provide compelling evidence that SP abundance significantly contributes to lung cancer progression and brain metastases via MMP-9–mediated ECM remodeling." (PMID 40321254, 2025). "Our data further support the involvement of MMP9 and its macrophage‐derived forms in the complex regulatory networks governing lung cancer development and progression." (PMID 40847563, 2025). "MMP-9 levels increased when some lung diseases are presented as chronic obstructive pulmonary disease, lung cancer, pneumonia, etc., and it is continually secreted in the airways." (PMID 40700162, 2025). "MMP-9 is present in elevated levels of serum of lung cancer, although not in the bronchial lavage fluid of patients, and serves as a biomarker for lung cancer." (PMID 41002342, 2025). "OTUD7B inhibits the activation of NF-κ B by deubiquitinating TRAF3, which in turn promotes the transcription of MMP9, thereby exerting an inhibitory effect on the migration of lung cancer cells." (PMID 39759114, 2025). "For instance, Skp2 is reported to promote the invasion via enhancing the expression of MMP-2 and MMP-9 in lung cancer oral squamous cell carcinoma." (PMID 41385185, 2025). "Artesunate significantly inhibits the growth of lung cancer (A549) cells by interfering with cell cycle progression, reducing the protein expression of Bcl-2 and MMP-9, and increasing the protein expression of Bax." (PMID 40490812, 2025). "In this study, we aim to investigate the abundance of SP in lung cancer tissues and its association with MMP-9 and MMP-2 expression, as well as its impact on survival outcomes in lung cancer patients." (PMID 40321254, 2025).
lung carcinoma (continued). "This study quantified SP abundance in lung cancer tissues and investigated its relationship with MMP-9 and MMP-2 expression, as well as its impact on clinical outcomes." (PMID 40321254, 2025). "In lung cancer cells (A549), resveratrol (10 μM, 30 μM) decreased MMP-9 mRNA expression and activity and its promoter activity, without any significant impact on MMP-2." (PMID 39335164, 2024). "PAR2 knockdown alone or treatment with gefitinib decreased MMP2 and MMP9 expression in lung cancer cells." (PMID 38172304, 2024). "In late NSCLC downregulation of contractile genes such as TAGLN were also observed, but others such as MMP1, MMP9 and SPP1 were found to be upregulated, which have functions in matrix remodelling and invasion and are linked to poor prognosis in lung cancer." (PMID 38582812, 2024). "Gelatin zymography assay indicates the silymarin has ability to inhibit the MMP-2 and MMP-9 expression in lung cancer." (PMID 39431222, 2024). "This analysis revealed significant differences in the expression of MMP-2 and MMP-9 between healthy individuals and those with lung cancer." (PMID 39431222, 2024). "Clinical studies on lung cancer bone metastasis have found that overactivation of MMP2/MMP9 promotes osteolytic metastasis and bone destruction in advanced cancer." (PMID 38571500, 2024). "Hyperglycemia induces MMP2 expression in cholangiocarcinoma by activating STAT335, upregulates MMP9 in lung cancer by inducing HMOX136, and upregulates MMP2/9 in breast cancer." (PMID 38200154, 2024). "This is consistent with a recent study that demonstrated CCR2 antagonism similarly downregulated MMP-9 in lung cancer cells, resulting in reduced cellular motility." (PMID 38228786, 2024). "This work explored the inhibitory effects of silymarin on lung cancer metastasis and revealed the underlying processes, focusing on matrix metalloproteinase (MMP) 2 and MMP-9 activities." (PMID 39431222, 2024). "Our study's findings highlight silymarin's potential as a potent inhibitor of MMP-2 and MMP-9 in A549 lung cancer cells." (PMID 39431222, 2024). "Hyaluranon is known to stimulate expression of various MMPs including MMP2 and MMP9 in skin fibroblasts, keratinocytes, and lung cancer cells." (PMID 39018235, 2024). "Our results showed that chia extracts; alcohol and ether significantly reduced expression levels of the studied genes c-MYC (by about 96 and 80%) and MMP9 (by about 69 and 60%) compared to the lung cancer group (p ≤ 0.05)." (PMID 39338293, 2024). "The data shown that MMP-2 and MMP-9 expression levels increase with advancing nodal stages, highlighting their crucial roles in lung cancer metastasis and progression." (PMID 39431222, 2024). "Another compound, honokiol, derived from Magnolia officinalis, was found to inhibit migration and invasion in H1299 lung cancer cells by disrupting the expression of MMP‐9 and the Hsp90/MMP‐9 interactions mediated by HDAC6." (PMID 37697969, 2023). "We analyzed the association of the polymorphism frequencies of MMP-2-735C/T and MMP-9-1562C/T with MMP-2 and MMP-9 serum concentrations, as well as their potential effects in lung cancer patients." (PMID 37445754, 2023). "Our findings are in agreement with other studies, which showed that p38MAPK inhibition resulted in decreased MMP-9 activity in leukaemia and lung cancer cells." (PMID 36882818, 2023). "Matrix metallopeptidase 9 (MMP9) is a matrixin that is involved in the degradation of the extracellular matrix as well as associated with hypertension, diabetes, obesity, and lung cancer as a marker gene." (PMID 36685671, 2023). "It is reported that MMP-9 is related to invasion, metastasis and prognosis of lung cancer, and those with high expression of it are prone to metastasis." (PMID 36690987, 2023). "Further, the binding stability of the daidzein–MMP9 complex was determined, as MMP9 is considered to be the most important target proteins in the lung cancer metastasis." (PMID 37764733, 2023).
lung carcinoma (continued). "DLK1 is known to affect MMP9 expression levels through NOTCH signaling to promote lung cancer cell invasion." (PMID 35163478, 2022). "Several studies have confirmed that POSTN, MMP9, and VCAM1 are implicated in regulating the incidence and development of solid tumors such as lung cancer, gastric cancer, and rectal cancer." (PMID 35965624, 2022). "HIF‐1α was also found to both modulate ALDOA expression and increase lactate levels, leading to upregulation of MMP9, thereby promoting an invasion of lung cancer cells in vitro and in vivo." (PMID 35615976, 2022). "It has been reported that under serum-depleted conditions, Rab37-mediated exocytosis of TIMP1 suppresses MMP9, which leads to decreased metastases of lung cancer cells in vivo." (PMID 36457117, 2022). "Nevertheless, the synergistic effect of curcumin and radiation suppressed MMP9 protein levels, which, in turn, inhibited E-cadherin levels, hence reducing the rate of invasion and metastasis of lung cancer cells." (PMID 36015440, 2022). "Inhibiting the expression of MMP-9 in lung cancer H1299 cells cultured in vitro can suppress early metastasis." (PMID 35361045, 2022). "The combination treatment inhibited invasion and migration of lung cancer cells, as shown by the downregulation of MMP9, Vimentin and N-cadherin, while overexpressing the E-cadherin expression level." (PMID 36015440, 2022). "A large number of scientific studies have shown that MMP2 and MMP9 are highly expressed in lung cancer tissues." (PMID 35814022, 2022). "For example, in bladder tissues, uc.8+ traps miR-596 and lowers the availability of this miRNA to bind MMP9 mRNA, while, in lung cancer cells, uc.339 acts as a decoy RNA for 3 miRNAs, including miR-339-3p, miR-663-3p, and miR-95-5p." (PMID 36214222, 2022). "Some studies reported the association between increased levels of MMP-2, MMP-9 and decreased TIMP-1 in early stage lung cancer." (PMID 36518397, 2022). "Taurine was found to inhibit the proliferation of lung cancer cells, significantly boosted the apoptosis rate, and reduced the expression of migration factors matrix metallopeptidase 9 (MMP-9) and vascular endothelial growth factor (VEGF)." (PMID 36457513, 2022). "In conclusion, we found that rhein inhibits cell proliferation and migration through the Stat3/Snail/MMP2/MMP9 pathway in lung cancer cells." (PMID 35178453, 2022). "Under basal conditions, MMP-9 levels are generally low, but overproduction is related to alveolar destruction and emphysema, leading to various lung diseases, such as lung cancer, asthma, fibrosis, and interstitial lung diseases." (PMID 35326218, 2022). "According to clinical studies, MMP-9 has high expression not only in lung cancer tissues but also in serum of patients, as an important reference index for the early diagnosis and prognostic evaluation of NSCLC patients." (PMID 35361045, 2022). "In conclusion, ART obviously suppressed the proliferation, migration and invasion but promoted the apoptosis of human lung cancer A549 and H1299 cells and also reduced the protein expression levels of HuR and MMP-9." (PMID 35361045, 2022). "In one study, lung cancer-derived exosomes induced fibroblast reprogramming into CAFs, with the exosomes overexpressing miR-210 as well as other proangiogenic factors such as MMP9, VEGFA, and FGF2, thus stimulating an increased level of angiogenesis." (PMID 34281588, 2021). "In this study, we successfully fused A549 Cm with MMP-9-switchable peptide-based charge-reversal liposome membranes and prepared integrated hybrid nanovesicle–cancer liposome-coated NPs for treating lung cancer in vivo." (PMID 34689761, 2021). "Upregulated matrix metallopeptidase 2 (MMP‐2) and matrix metallopeptidase 9 (MMP‐9) promote migration of lung cancer cells." (PMID 33931980, 2021). "STAT3 curbs the RECK expression and increases the activity of MMP-2 and MMP-9 in lung cancer cells by up-regulation of miR-92a, promoting the malignant biological behavior of cells." (PMID 34790697, 2021).
lung carcinoma (continued). "This also upregulates HOXA10, MMP‐2, and MMP‐9, contributing to migration of lung cancer cells and ultimately reducing radiosensitivity." (PMID 33931980, 2021). "For example, in breast, kidney or lung cancer cells, MMP9 (matrix metalloproteinase 9) and ADAM19 (Adam metallopeptidase 19) metalloproteinase expression during EMT are modulated by changes in histone methylation marks." (PMID 34067395, 2021). "We have previously shown that Anthos favorably modulate targets such as β-catenin, cyclin D1, cyclin B1, pERK, VEGF proteins, c-myc and MMP9 in lung cancer H1299 cells." (PMID 34926717, 2021). "Highly expressed MMP-2 and MMP-9 have been found in lung cancer tissue and are closely related to poor prognosis in patients with lung cancer." (PMID 33758209, 2021). "In this study, we found that downregulation of miR-101-3p in CAFs upregulated the expression of MMP9 and Twist1 in lung cancer cells." (PMID 34977016, 2021). "Progression of different types of cancer including lung cancer has been reported to be associated with overexpression of both MMP2 and MMP9 and correlates with metastasis and poor prognosis." (PMID 34209215, 2021). "We have previously shown that MKL1 is a transcriptional activator of matrix metalloproteinase 9 (MMP9) in lung cancer cells." (PMID 33898415, 2021). "Upon JMJD8 knockdown in lung cancer cell lines, cyclin B1, RhoA, RhoC, MMP9, and N-cadherin were down-regulated, and p21 and E-cadherin were conversely up-regulated." (PMID 33442397, 2021). "The role of EMT biomarkers FN1 and VIM and the matric metalloproteinases, MMP-9 and MMP-7, in lung cancer in the background of ALK mutation is under study." (PMID 33091333, 2021). "The expression level of IL-6 was measured by IL-6 sandwich ELISA after treating human lung carcinoma cell line A549 with IL-1β and Canakinumab, pro-Canakinumab, MMP-9 pre-incubated Canakinumab or MMP-9 pre-incubated pro-Canakinumab, respectively." (PMID 34290297, 2021). "The upregulation of Arhgap6 gene is critically important in preventing and treating lung cancer through the suppression of matrix metalloproteinase−9 (MMP9) and vascular endothelial growth factor (VEGF)." (PMID 34367133, 2021). "A significant association between MMP-9 and HIF-1α expression was reported in studies of lung cancers." (PMID 35280249, 2021). "Gene 33 expression has an inverse relationship with tyrosine phosphorylation of EGFR and the expression of metalloproteases MMP-2 and MMP-9 in lung cancer cells, suggesting a role of Gene 33 in lung cancer cell migration, invasion, and metastasis." (PMID 34206547, 2021). "Based on this evidence and our finding, the reduction in MMP-2 and MMP-9 expressions induced by ETD in lung cancer cells is a consequence of inactivation of Akt and its downstream effectors." (PMID 33758209, 2021). "CK mixed with miscells (20 μg/mL) successfully lowered protein levels of MMP-9 in A549 lung cancer cells, resulting in declined migration and invasion in mice bearing A549 cells." (PMID 33671187, 2021). "Based on the previous reports regarding the role of air pollutants on the MMP activity in pulmonary diseases, we investigated the MMP-2 and MMP-9 expressions in PM10-exposed A549 lung cancer cells." (PMID 33374928, 2020). "Meanwhile, honokiol‐suppressed MMP‐9 expression and invasion ability of H1299 lung cancer cells was rescued by HDAC6 overexpression." (PMID 32180962, 2020). "The suppression of migration and invasion activities of honokiol was through inhibiting HDAC6‐mediated Hsp90/MMP‐9 interaction and followed by MMP‐9 degradation in lung cancer." (PMID 32180962, 2020). "Here, we show that lung CSC‐derived exosomes promote the migration and invasion of lung cancer cells, up‐regulate expression levels of N‐cadherin, vimentin, MMP‐9 and MMP‐1, and down‐regulate E‐cadherin expression." (PMID 32396269, 2020).
lung carcinoma (continued). "The increased macrophage infiltration and higher MMP9 productions constitute a tumor microenvironment for promoting the lung cancer cell invasion." (PMID 32356397, 2020). "PRDX4 was critical for the activation of AP-1 signaling, and depletion of PRDX4 leads to reduced phosphorylation of c-Jun and decreased expression of MMP9, which contributes to the malignancy of human lung cancer cells." (PMID 33456675, 2020). "For instance, an interaction between MRTF-A and the histone H3K4 methyltransferase complex COMPASS results in activation of MMP9 transcription and augmented migration/invasion of lung cancer cells." (PMID 32999272, 2020). "This interaction can lead to increased infiltration, M2‐type polarization, MMP9 production of macrophages, and a feedback induction of ERα expression of lung cancer cells." (PMID 32356397, 2020). "Previous study showed that MMP-9 derived from sublethally irradiated lung carcinoma cells plays an important role in radioresistance and in initiating metastatic cascades." (PMID 32143669, 2020). "According to database analysis, we found that expression of NIK correlated significantly and positively with IL-2 or MMP9 expression in lung cancer patients." (PMID 33198776, 2020). "In contrast, decreasing ERα via adding lentiviral shERα #1 and shERα #2 in lung cancer H1299 cells can reduce the MMP9 mRNA expression in cocultured THP‐1 cells (middle)." (PMID 32356397, 2020). "We also verified that lung CSC‐derived exosomes enhanced the migratory and invasive abilities of lung cancer cells; increased N‐cadherin, vimentin, MMP‐9 and MMP‐1 expression; and decreased E‐cadherin expression." (PMID 32396269, 2020). "Previous studies have demonstrated that the suppression of STAT3 phosphorylation and VEGF expression, as well as inhibition of MMP-2 and MMP-9, contributes to alleviating the invasion and angiogenesis process of lung cancer cells by curcumin." (PMID 33511113, 2020). "Our results show that CCL2 is directly regulated by ERα, and the increased CCL2 in lung cancer cells can further influence the M2 polarization and MMP9 production of macrophages." (PMID 32356397, 2020). "Lung cancer cell lines with successfully downregulated MMP-9 expression were selected by western blotting." (PMID 32238777, 2020). "We found that erianin suppressed the migration of lung cancer cells by downregulating the mesenchymal markers vimentin, N-cadherin, slug, snail, and MMP-9 and upregulating the epithelial marker E-cadherin." (PMID 32382060, 2020). "Following co-culture with MSCs and FACS sorting, we detected a profound and selective induction of MMP9 mRNA expression in lung cancer cells among the cohort of MMP transcripts evaluated." (PMID 33119681, 2020). "Previous reports also indicated that the downregulation of MMP-2 and MMP-9 inhibits the invasion and metastasis of lung cancer cells." (PMID 32349289, 2020). "Past studies have found that MMP2 and MMP9 were highly expressed in lung cancer and essential for the growth and metastasis of lung tumors." (PMID 33304892, 2020). "Further, depletion of ABL kinases in lung cancer cells decreased the MSC-mediated expression of secreted MMP9 protein in PC9 and HCC827 lung cancer cells compared to the corresponding control cells." (PMID 33119681, 2020). "To assess the extent to which direct co-culture of lung cancer cells with MSCs affected MMP9 enzymatic activity, we employed a gelatin zymography assay." (PMID 33119681, 2020). "MSCs elicit transcriptional alterations in lung cancer cells leading to increased expression of factors implicated in the epithelial-to-mesenchymal transition (EMT) and secreted proteins including matrix metalloproteinase-9 (MMP9)." (PMID 33119681, 2020). "Knockdown of PD-L1 suppressed the expression of N-cadherin, Vimentin, MMP-9 and Claudin-1 but upregulated E-cadherin expression in lung cancer cells." (PMID 32632098, 2020).